ALKBH5 (alkB homolog 5, RNA demethylase)
Diseases named in the same sentence as ALKBH5 in open-access papers (continued):
Sharing a sentence is not in itself a finding about the gene and the disease.
cancer (continued). "A study revealed that in multiple cancer cell lines, when ALKBH5 is silenced, the demethylation of m6A in ER lipid raft associated 1 (ERLIN1) mRNA is reduced, and an increase in the expression of the LC3B, a subtype of LC3, is observed, leading to increased autophagic flux." (PMID 39468015, 2024). "RNA modification has become a focal point in cancer research, and while the role of ALKBH5 has been established in regulating endothelial cell angiogenesis via a SPHK1 dependent manner under ischemic stress, but the crosstalk between RNA modification and angiogenesis of GBM has been less explored." (PMID 38221546, 2024). "Increasing research has focused on exploring the mechanisms responsible for the dysregulation of ALKBH5 in cancers: Hypoxia: ALKBH5 is a direct target of HIF‐1α, indicating that ALKBH5 may be involved in the regulation of cellular responses to hypoxia." (PMID 36260366, 2023). "ALKBH5 is dysregulated and plays biological and pharmacological roles in human cancers." (PMID 37612282, 2023). "The anti-cancer effects of ALKBH5 (including suppression of cell proliferation, migration and invasion) were partly restored by silencing of FABP5 which indicated FABP5 could be downstream gene of ALKBH5." (PMID 37416772, 2023). "Since ALKBH5 knockout mice are viable and anatomically normal, except for impaired fertility, our results suggest that normal cells and cancer cells may have different mechanisms and thresholds to negotiate ER stress." (PMID 37174684, 2023). "The role of ALKBH5 in cancer development varies depending on the tissue origin of cancer." (PMID 37325047, 2023). "Additionally, studies have shown that knockout ALKBH5 can induce G1 phase arrest, inhibit the cancer cell proliferation, and increase the number of apoptotic cells." (PMID 38094306, 2023). "Our results showing the induction of the UPR in ALKBH5-silenced cancer cells suggest that inhibiting ALKBH5 may be a novel approach for new drugs to treat cancers that depend on ALKBH5 pro-tumorigenic signaling." (PMID 37174684, 2023). "Previous studies have shown that FTO and ALKBH5 play a cancer-suppressive role in CRC." (PMID 37580808, 2023). "Recently, research on ALKBH5 in disease has been focused primarily on cancer." (PMID 36899424, 2023). "In addition, the expression of connective tissue growth factor (CTGF), which is a direct target of angiogenesis-promoting medium and the TGFβ signalling pathway, is significantly reduced in METTL14/ALKBH5-silenced cancer cells." (PMID 38053093, 2023). "K235 acetylation of ALKBH5 is upregulated in cancers and promotes tumorigenesis." (PMID 37369679, 2023). "Additionally, ALK-04, a small-molecule ALKBH5 inhibitor, enhanced the efficacy of cancer immunotherapy." (PMID 37990254, 2023). "Above all, everolimus, a pharmacological mTOR inhibitor widely used for advanced pNENs patient treatment, the lower expression of ALKBH5 may further synergize with everolimus to suppress mTOR activation and inhibit cancer cell growth." (PMID 37858219, 2023). "This could also explain the close relationship between ALKBH5 and cancer progression under hypoxic conditions reported by other groups." (PMID 37742191, 2023). "A previous study indicated that ALKBH5 was a cancer‐promoting gene in GC." (PMID 36864711, 2023). "ALKBH5 demethylated mRNAs to promote or suppress proliferation in many cancers 26,27." (PMID 36632222, 2023). "Similarly, four representative CRC tissues showed lower FTO and ALKBH5 expression levels than the corresponding para-cancer tissues." (PMID 37580808, 2023).
cancer (continued). "Therefore, the role of this enzyme remains controversial, possibly due to the different cancer models, and the mechanism of action of ALKBH5 in GC needs further investigation." (PMID 36864711, 2023). "There has been an increase in research into the mechanisms of ALKBH5 dysregulation in cancer." (PMID 36899424, 2023). "Another study investigated the role of ALKBH5 in cancer development, indicating that it may stabilize oncogenes and accelerate cancer progression." (PMID 37998339, 2023). "Screening m6 A levels by silencing the demethylase ALKBH5 inhibits cancer growth and angiogenesis." (PMID 38053093, 2023). "ALKBH5 not only plays a great role in cancers but also is critical for non-cancer diseases." (PMID 37598390, 2023). "ALKBH5 expression can be induced by hypoxia and HIF1α in cancer cells." (PMID 37369679, 2023). "Human AlkB homolog H5 (ALKBH5) could demethylate long noncoding RNAs, promote cancer cell self-renewal, or regulate autophagy in malignancies, playing a fundamental role in noncancerous reproductive system illnesses in humans." (PMID 36157216, 2022). "ALKBH5 was reported to exert opposite roles in different kinds of cancers, indicating that it may regulate different m6A methylation profiles in a different context." (PMID 35530319, 2022). "Finally, we used Targetscan, miWalk, miRDB, miRabel and other websites to identify ALKBH5-targeting miRNAs and lncRNAs and constructed a lncRNA-miRNA-ALKBH5 regulatory network that regulates the abnormal expression of ALKBH5 in various cancers." (PMID 35444654, 2022). "Finally, we then investigated the expression characteristics of the ALKBH5 protein in 43 different normal tissues and various cancers using the THPA database, respectively." (PMID 35444654, 2022). "However, in the field of cancer research, the potential mechanisms of ALKBH5 are not only unclear but also disputed." (PMID 35279083, 2022). "The inhibitor of Alkbh5 has been shown to improve the effectiveness of cancer immunotherapy." (PMID 36620557, 2022). "Since ALKBH5 has opposite, context-dependent functions in cancer, approaches to both induce and suppress ALKBH5 could represent viable treatment options for malignancies." (PMID 35063010, 2022). "AlkB homolog 5 (ALKBH5) is another key m6A demethylase for gene transcription, translation, and metabolism, and is regarded as an effective biomarker for various diseases, especially cancers." (PMID 36035182, 2022). "This review summarized recently reported progress in understanding ALKBH5’s structure and up-to-date findings concerning ALKBH5’s roles in cancer, with a main focus on the regulatory effects of ALKBH5 on diverse targets in cancer and how ALKBH5 is dysregulated in cancer." (PMID 35063010, 2022). "Recent research has illustrated the functions and mechanisms of ALKBH5 in cancer immunotherapy." (PMID 35628623, 2022). "According to Na Li’s findings, tumors are more susceptible to cancer immunotherapy in the absence of the m6A demethylase Alkbh5." (PMID 36620557, 2022). "The pan-cancer analysis showed that ALKBH5 was upregulated in several solid tumors." (PMID 35444654, 2022). "There are very few studies on ALKBH5-mediated modification of lncRNAs in cancers." (PMID 36376862, 2022). "In addition, ALKBH5 inhibited cancer progression by regulating PD-L1, CK2α, LYPD1, PER1, WIF-1, and lncRNA KCNK15-AS1 expression." (PMID 35945641, 2022). "It is reported that ALKBH5 plays a vital and specific role in cancer regulation." (PMID 35979628, 2022). "And deletion of ALKBH5 sensitized tumors to cancer immunotherapy." (PMID 35371987, 2022). "In addition, the role of ALKBH5 in disease has been most extensively studied in the context of cancer." (PMID 35063010, 2022). "Therefore, in this study, comprehensive bioinformatics analysis of pan-cancer datasets was performed to determine the mechanisms through which ALKBH5 regulates tumorigenesis." (PMID 35444654, 2022).
cancer (continued). "ALKBH5 is a major demethylase, and plays vital roles in the progression of cancers." (PMID 35979628, 2022). "ALKBH5 expression correlated with the expression of multiple ICP genes in multiple cancers." (PMID 35444654, 2022). "However, in actual human cancers, ALKBH5 catalyzes specific m6A of numerous genes, which simultaneously alters several RNA and protein expressions through RNA recognition by reader proteins, consequently causing numerous interactions between them in vivo." (PMID 35318440, 2022). "Meanwhile, increasing non-coding RNAs are recognized as functional targets of ALKBH5 in cancers." (PMID 35063010, 2022). "In addition, The silencing of ALKBH5 significantly promotes proliferation, migration and metastasis of cancer cells." (PMID 35022030, 2022). "However, it is increasingly clear that the effect of ALKBH5 on the cancer cell is determined by the cellular context in which it is present and the functional targets it regulates." (PMID 35063010, 2022). "The findings that ALKBH5 is dysregulated and plays critical roles in multiple cancers support the hypothesis that targeting ALKBH5 can act as an approach to cure different types of cancer." (PMID 35063010, 2022). "ALKBH5 expression significantly correlated with the prognosis of cancer patients." (PMID 35444654, 2022). "We evaluated m-6-A modified protein, which showed IMPDH1 was closely related to m-6-A related regulatory proteins in pan-cancer, and we focused on evaluating the association of IMPDH1 with the top four proteins: YTHDF1, ALKBH5, YTHDF2, METTL3 in HCC, indicating a strong relationship." (PMID 36618420, 2022). "Therefore, we analyzed the relationship between expression levels of ICP genes and ALKBH5 in multiple cancer types." (PMID 35444654, 2022). "HNRNPA2B1, HNRNPC, LRPPRC, ALKBH5 showed high expression in almost all cancers." (PMID 35265626, 2022). "Thus, the role of ALKBH5 in cancer is mainly dependent on its functional targets in a specific cancer type or cellular context." (PMID 35063010, 2022). "ALKBH5 is an independent prognostic indicator in a variety of cancers." (PMID 35784761, 2022). "In this study, we identified lncNRON as a possible additional regulatory subunit of the RNA m6A eraser, which may partially explain the controversial function of ALKBH5 in cancers." (PMID 34659574, 2021). "In addition, ALKBH5 plays an essential role in the regulation of cancer cell proliferation and invasion." (PMID 33744868, 2021). "ALKBH5 exerts essential biological functions in several tumors and cancers." (PMID 35087575, 2021). "Mounting evidences state that ALKBH5 plays versatile roles in various cancers." (PMID 34733841, 2021). "These interesting roles of ALKBH5 in different cancers warrant further study." (PMID 35004679, 2021). "The aberrant function of ALKBH5 contributes to several types of cancers via specific mechanisms." (PMID 33790968, 2021). "ALKBH5 is an important component of the m6A modifying enzyme complex, and it has been reported that deletion of the m6A demethylase ALKBH5 can make patients more sensitive to cancer immunotherapy." (PMID 34660577, 2021). "The depletion of METTL3 is known to cause apoptosis of cancer cells and may reduce their invasiveness, while the activation of ALKBH5 by hypoxia has been shown to induce cancer stem cell enrichment." (PMID 34660259, 2021). "ALKBH5 has been shown to be involved in carcinogenesis and progression of a variety of cancers." (PMID 33428593, 2021). "Depending on the cell type, ALKBH5 exhibits divergent functions in cancers." (PMID 34491904, 2021). "Notably, a small-molecule ALKBH5 inhibiting element enhanced the efficacy of carcinoma immunotherapy." (PMID 34188972, 2021). "Alk B homologue 5 (ALKBH5) participates in the biological regulation of various cancers." (PMID 32329191, 2020). "ALKBH5 is also an independent prognostic indicator in various cancers." (PMID 32742194, 2020).
cancer (continued). "ALKBH5 could demethylate lncRNAs, enhance cancer cells self-renewal or regulate autophagy in cancers." (PMID 32742194, 2020). "In the majority of cancer research, the role of ALKBH5 in human cancers was controversial." (PMID 32742194, 2020). "In addition, other enrolled in cox formula m6A-related genes METTL14, YTHDF2, ALKBH5 played an oncogenic role in various cancers in a m6A- dependent manner." (PMID 32526707, 2020). "Notably, decreased ALKBH5 was closely connected with a shortened overall and cancer-specific survival following nephrectomy in ccRCC." (PMID 32742194, 2020). "Furthermore, our findings challenge the prevailing view that ALKBH5 is primarily an m6A demethylase, as its demethylase activity has been predominantly reported when it is upregulated in cancer, although several studies have also demonstrated its demethylase function also in noncancer research." (PMID 39746750, 2025). "Indeed, ALKBH5 can be a cancer suppressor by modulating the lipid metabolism of CESC." (PMID 40958857, 2025). "With deeper mechanistic insights and the development of selective inhibitors, ALKBH5 holds great promise as a novel immunotherapeutic target and predictive biomarker, offering new avenues and strategies to enhance the efficacy and precision of cancer immunotherapy." (PMID 41562066, 2025). "However, whether ALKBH5 or FTO are required for ATF4 mRNA translation in chemotherapeutic-treated cancer cells to promote resistance is still unknown." (PMID 39199320, 2024). "However, the role of ALKBH5 in human cancer is controversial." (PMID 38166832, 2024). "In addition, studies suggest that ALKBH5 is involved in inducing cancer immune escape." (PMID 39468015, 2024). "However, the role of ALKBH5 in cancer appears contradictory based on recent studies." (PMID 39039912, 2024). "Hence, dysregulated ALKBH5 expression could promote or suppress carcinogenesis based on cancer types." (PMID 36899424, 2023). "Therefore, from a therapeutic perspective, profiling the m6A modification pattern, particularly in ALKBH5-deficient HPSCC, may allow the development of treatments targeting RNA methyltransferases in cancer." (PMID 37612282, 2023). "Hence, a better understanding of the key targets of ALKBH5 in cancer cells could potentially lead to the development of new therapeutic targets." (PMID 37858219, 2023). "In addition, ALKBH5 was highly expressed in the majority of human cancers, including HNSCC." (PMID 35395767, 2022). "Therefore, m6A-mediated gene expression regulated by ALKBH5 could result in various consequences in cancer cells, depending on the surrounding environment and other factors." (PMID 35318440, 2022). "Therefore, ALKBH5 may be a potential predictive biomarker of immunotherapeutic responses in patients with malignant tumors." (PMID 35444654, 2022). "Besides, studies have shown that ALKBH5 is involved in the induction of cancer immune evasion." (PMID 35063010, 2022). "FTO and ALKBH5 were the main m6A demethylases, which could reverse RNA methylation by oxidizing the N-methyl group at m6A site to a hydroxymethyl group, and were involved in the development of immune diseases and cancer." (PMID 36619747, 2022). "Moreover, ALKBH5 promoted cisplatin resistance in cancer cells." (PMID 36517820, 2022). "Thus, various stress-induced epigenetic modifications, including m6A modification by ALKBH5, may be the reason for cancer’s immunotherapy resistance, which still requires further investigation." (PMID 36566230, 2022). "Potential strategies including small-molecule modulators, proteolysis targeting chimera (PROTAC), programmable m6A-editing systems, compounds targeting the regulatory machinery of ALKBH5, as well as gene therapy, could be applied to manipulate ALKBH5-mediated m6A demethylation in cancer." (PMID 35063010, 2022). "Therefore, ALKBH5 may also be a possible therapeutic target for treating cancer, alone, or with immune checkpoint blockade (ICB)." (PMID 36226062, 2022).
cancer (continued). "Therefore, potential tissue- or cell-specific differences in m6A reader proteins may alter ALKBH5’s regulation of downstream targets and explain the conflicting functions of ALKBH5 in cancers." (PMID 35063010, 2022). "Altered ALKBH5 expression could both promote and suppress carcinogenesis, based on cancer type." (PMID 35063010, 2022). "Whether such approach would degrade ALKBH5 in cancer deserves further attention." (PMID 35063010, 2022). "Furthermore, IHC revealed ALKBH5 protein to be primarily located in the nucleus of cancer cells." (PMID 34491904, 2021). "However, the function of ALKBH5 in cancer is still controversial." (PMID 33428593, 2021). "Also, the deletion of the m6A demethylase Alkbh5 sensitized tumors to cancer immunotherapy." (PMID 34630412, 2021). "Therefore, ALKBH5 may be a promising therapeutic target to help improve cancer immunotherapy outcomes." (PMID 34794452, 2021). "Interestingly, ALKBH5 acts as a profound regulator in the maintenance and differentiation of cancer stem cells (CSCs), which is necessary for the formation and metastasis of primary cancers." (PMID 34211849, 2021). "Furthermore, ALKBH5 played a great role in human non-cancers, such as reproductive system diseases." (PMID 32742194, 2020). "Beyond cancer, curcumin increased m6A on TRAF4 mRNA by inhibiting ALKBH5, which in turn enhanced YTHDF1-dependent TRAF4 translation and suppressed adipogenesis." (PMID 41322307, 2025). "In particular, ALK-04 inhibits the ALKBH5-mediated upregulation of MCT4, leading to reduced lactate export to the TME and increased efficacy of cancer immunotherapy." (PMID 41373022, 2025). "Fatty acid binding protein 5 (FABP5) mRNA is m6A‐modified, but upregulation of ALKBH5 increases FABP5 expression by decreasing m6A modification, inducing fatty acid synthesis via PI3K/AKT/mTOR signaling pathway and promoting cancer growth." (PMID 40448344, 2025). "In lung adenocarcinoma (LUAD), m6A modification via METTL3 upregulation and ALKBH5 downregulation increases ENO1 translation, promoting glycolysis and providing energy for cancer cell proliferation." (PMID 39802639, 2025). "Recently, curcumin has been shown to affect RNA methylation (m6A) by regulating writer (METTL3/METTL14), eraser (ALKBH5/FTO), and reader (YTHDF1/2) proteins, thereby altering mRNA stability and translation in cancer, inflammatory, and metabolic contexts." (PMID 41322307, 2025). "Core enzymes such as METTL3, ALKBH5 and IGF2BP proteins play essential roles not only in cancer but also in normal tissue homeostasis, raising concerns about toxicity and selectivity when targeting these proteins therapeutically." (PMID 41228380, 2025). "m6A regulators include writers (METTL3, METTL14, KIAA1429, and ZC3H13), erasers (ALKBH5 and FTO) and readers (YTHDF1/2/3, IGF2BP1/2/3), which are thought to play important roles in regulating cancer progression." (PMID 40774945, 2025). "HIF1α/HIF2α induce ALKBH5 (alkB homolog 5, RNA demethylase) expression during hypoxic conditions that demethylate Sox2 mRNA (m6A-modified mRNAs), leading to Sox2/CD133 upregulation and maintenance of cancer stem-like traits." (PMID 37922108, 2024). "Therefore, we posit that ALKBH5, through its regulatory action on TTI1 expression, serves as a pivotal determinant in either promoting or inhibiting specific malignancy-associated cellular behaviors in HCC, underlining a sophisticated network of genetic interactions pivotal to cancer cell dynamics." (PMID 38501918, 2024). "We collected PB from healthy controls (HCs) and patients with CRC, analyzed PB RNA m6A levels and the expression of m6A-related demethylase genes FTO and ALKBH5, cocultured CRC cells with PB mononuclear cells (PBMCs), and constructed an MC38 cancer model." (PMID 38439072, 2024).